SDHD (succinate dehydrogenase complex subunit D)
Description:
Membrane-anchoring subunit of succinate dehydrogenase (SDH) that is involved in complex II of the mitochondrial electron transport chain and is responsible for transferring electrons from succinate to ubiquinone (coenzyme Q). SDH also oxidizes malate to the non-canonical enol form of oxaloacetate, enol-oxaloacetate (By similarity). Enol-oxaloacetate, which is a potent inhibitor of the succinate dehydrogenase activity, is further isomerized into keto-oxaloacetate (By similarity).
Synonyms: CybS; SDH4; CBT1; CII-4; CWS3; MC2DN3; PGL; PGL1; PPGL1; QPs3
Tractability: Small molecule: a structure with a bound ligand is known. Antibody: UniProt predicts a signal peptide or a membrane-spanning region. PROTAC: its protein half-life has been measured.
Gene: Protein-coding gene on chromosome 11 (112,086,824 to 112,120,016, forward strand). Ensembl gene ENSG00000204370.
Subcellular location: Mitochondrion inner membrane
Pathways (Reactome):
Metabolism: Citric acid cycle (TCA cycle); Maturation of TCA enzymes and regulation of TCA cycle; Respiratory electron transport
Gene Ontology:
Molecular function: protein binding; electron transfer activity; heme binding; ubiquinone binding; succinate dehydrogenase (quinone) activity
Biological process: tricarboxylic acid cycle; mitochondrial electron transport, succinate to ubiquinone; proton motive force-driven mitochondrial ATP synthesis
Cellular component: mitochondrial inner membrane; mitochondrion; respiratory chain complex II (succinate dehydrogenase); mitochondrial envelope; membrane; mitochondrial matrix
Genetic constraint (gnomAD): Loss-of-function variants: 4 observed, 15.76 expected, observed/expected ratio (o/e) 0.25, 90% interval 0.12 to 0.58. The upper end of that interval is the gene's LOEUF score, 0.58, which puts it in group 2 of 6, group 1 being the genes least tolerant of losing a copy. Missense variants: 145 observed, 174.2 expected, observed/expected ratio (o/e) 0.83, 90% interval 0.73 to 0.95. Synonymous variants: 53 observed, 67.66 expected, observed/expected ratio (o/e) 0.78, 90% interval 0.63 to 0.99.
Gene-disease validity (ClinGen):
ClinGen rates the evidence that SDHD causes each of these diseases.
hereditary pheochromocytoma-paraganglioma (autosomal dominant): Definitive. Neoplasm predisposition characterized by an increased risk of paragangliomas (tumors that arise from neuroendocrine tissues distributed along the paravertebral axis from the base of the skull to the pelvis) and pheochromocytomas (paragangliomas that are confined to the adrenal medulla).
mitochondrial disease (autosomal recessive): Limited.
Homologues: Orthologues: chimpanzee SDHD (99% identical), macaque SDHD (96% identical), dog SDHD (86% identical), guinea pig SDHD (84% identical), mouse Sdhd (82% identical), pig SDHD (72% identical), tropical clawed frog sdhd (60% identical), zebrafish sdhdb (59% identical), zebrafish sdhda (52% identical), Caenorhabditis elegans sdhd-1 (33% identical), Drosophila melanogaster SdhD (31% identical).
Diseases named in the same sentence as SDHD in open-access papers:
SDHD is named in the same sentence as 127 diseases in open-access papers, as found by Europe PMC text mining. Sharing a sentence is not in itself a finding about the gene and the disease. The quoted sentences say what the papers report.
paraganglioma (97 papers, 2004 to 2025). A benign or malignant neoplasm arising from paraganglia located along the sympathetic or parasympathetic nerves. "Of the total study population, 18% developed a paraganglioma, which is higher than the prevalence in the similar study from France (8%).13This difference in prevalence is probably due to the high proportion of SDHD variant carriers in the Netherlands." (PMID 39881751, 2025). "All patients diagnosed with a paraganglioma on definitive diagnosis had a related SDHD germline mutation." (PMID 38368490, 2024). "In human patients with paragangliomas, those carrying SDHD germline mutations face a significantly higher risk of developing distant metastases, making this mutation a critical indicator of potential malignant progression." (PMID 39591360, 2024). "Although in humans, genetic studies have shown that 87.1% of cases of paragangliomas are associated with mutations in the SDHD gene." (PMID 39649680, 2024). "Two previous studies investigating the role of the SDHD gene in canine endocrine neoplasias demonstrated that a synonymous mutation (c.365A>G, p.Lys122Arg) in dogs is associated with the presence of paragangliomas (PGL) and pheochromocytomas (PCs)." (PMID 39591360, 2024). "Polish patients with paragangliomas often carry SDHD c.33C>A (p.Cys11*) variant; all subjects with this allele have identical haplotypes indicating a founder effect." (PMID 39273284, 2024). "Researchers worldwide reported that head and neck paragangliomas (solitary or multiple) represent a strong predictor for SDHD mutation even in small cohort of patients." (PMID 38144572, 2023). "Two patients had bilateral tumors (4.3%), and in one patient with a family history of paragangliomas, an SDHD-gene mutation was found." (PMID 36832232, 2023). "Overall, patients with SDHA-mutant tumors tend to have an older median age compared to the SDH-deficient GISTs due to other subunit mutations, while SDHB, SDHC, and SDHD mutant GISTs usually also develop paragangliomas." (PMID 36980917, 2023). "It should be considered, that there is a high prevalence of occult paragangliomas in asymptomatic carriers of SDHD and SDHB gene mutations." (PMID 38144572, 2023). "Paragangliomas with SDHD mutations have been reported to have a frequency of metastatic tumors of 1–9%." (PMID 36138281, 2022). "Germline mutation of the succinate dehydrogenase subunit genes, SDHA, SDHB, SDHC or SDHD, is associated with increased risk for paraganglioma (PGL), pheochromocytoma (Pheo), gastrointestinal stromal tumor (GIST) and renal cell carcinoma." (PMID 36455002, 2022). "Although major disruption of this cycle was a natural predicted outcome once loss of SDHD was identified as a cause of paraganglioma, interest in the cellular biochemistry of PPGL/HNPGL tumors has gathered pace only relatively recently." (PMID 35741787, 2022). "Earlier studies recognized that loss-of-function mutation of SDHD in paraganglioma was associated with elevated HIF-1α which led to the proposal that SDH mutation results in activating hypoxia response pathway." (PMID 36344992, 2022). "The weight of the evidence to attach to observation of a novel rare missense variant in SDHB or SDHD in individuals with the rare neuroendocrine tumors, pheochromocytomas and paragangliomas (PCC/PGL), is uncertain." (PMID 34906457, 2022). "His father and 22-year-old brother tested positive for succinate dehydrogenase complex subunit D (SDHD) mutation and his brother had one abdominal and two thoracic paragangliomas." (PMID 33715142, 2021). "To our knowledge, we report the first patients with increased IL-6 production in the presence of SDHD mutation related paragangliomas and lesions suspicious for metastases." (PMID 33715142, 2021).
paraganglioma (continued). "The pooled incidence for malignant paragangliomas is about 8% in SDHD mutation carriers, whilst for SDHB, it can be as high as 41%." (PMID 34072806, 2021). "Mutations in the SDHD gene are one of the causes of pheochromocytoma and paraganglioma, paragangliomas being the most prevalent type of CB cancer." (PMID 34070267, 2021). "Another study on SDHB, SDHC, and SDHD gene mutation analysis in a large cohort of patients with a personal or family history of paragangliomas/pheochromocytomas was performed." (PMID 32948182, 2020). "The identified germline variant in the SDHD gene seems to be a driver in the development of multiple paragangliomas." (PMID 32948182, 2020). "The variant in the SDHD gene identified in the study has been described only once in a malignant paraganglioma." (PMID 32948182, 2020). "Mutations in VHL, RET, NF1, SDHB, and SDHD account for 90% of all pheochromocytomas and paragangliomas." (PMID 32266384, 2020). "SDHB (10.3%) and SDHD (8.9%) mutations are the most frequent germline mutations in pheochromocytoma and paragangliomas." (PMID 32266384, 2020). "We identified a likely pathogenic germline variant in the SDHD gene and likely pathogenic somatic variants in a number of genes in the patient with multiple paragangliomas (left and right CPGLs, and VPGL)." (PMID 32948182, 2020). "Germline variants in SDHC are more rarely associated with the development of paragangliomas/pheochromocytomas than variants in SDHB or SDHD." (PMID 30871634, 2019). "This pattern has been reported 3.7–11.5% of paragangliomas/pheochromocytomas and was frequently identified in cases with SDHD and SDHB mutations." (PMID 30971719, 2019). "Mutations in SDHB or SDHD were identified in 10 out of 10 patients with mediastinal paragangliomas, a rare location for paraganglioma development (2%)." (PMID 30456751, 2018). "SDHD gene mutations are associated with multifocal head and neck paragangliomas and less commonly with adrenal pheochromocytomas or paragangliomas at other sites." (PMID 30456751, 2018). "VHL, RET, NF1, SDHB, and SDHD are major susceptibility genes, accounting for 90% of familial pheochromocytomas/paragangliomas, whereas TMEM127, SDHA, SDHC, SDHAF2, and MAX are minor susceptibility genes responsible for 10% of these tumors." (PMID 30456751, 2018). "Succinate dehydrogenase subunit B and D (SDHB and SDHD) mutations represent the most frequent cause of hereditary pheochromocytoma and paraganglioma (PPGL)." (PMID 30106970, 2018). "To investigate the extent and nature of chromosome 11 loss across the various paraganglioma subgroups, we assembled a panel of 26 SDHD, 13 SDHB, and 8 VHL-related PGLs/PCCs." (PMID 28099933, 2017). "Germline mutations in the four genes encoding SDH subunits (SDHA, SDHB, SDHC and SDHD) are linked to the development of neuroendocrine tumors such as pheochromocytomas and paragangliomas." (PMID 28911113, 2017). "Germline mutations in the succinate dehydrogenase complex genes SDHB, SDHC, and SDHD predispose to pheochromocytomas and paragangliomas." (PMID 27279923, 2016). "Here, we examine the SDHB, SDHC, and SDHD mutation spectrum in the Danish population by screening of 143 Danish pheochromocytoma and paraganglioma patients." (PMID 27279923, 2016). "Mutations in the CII subunit genes SDHA, SDHB, SDHC and SDHD have also been associated with paragangliomas and pheochromocytoma." (PMID 26839416, 2016). "Thirdly, we confirmed loss of SDHD expression, a phenomenon associated with “benign” conditions in other tumors e.g., paragangliomas." (PMID 25023465, 2014). "Here we explore the underlying molecular basis of three cases of paraganglioma or pheochromocytoma that came to our attention due to apparent maternal transmission of an SDHD mutation." (PMID 25300370, 2014). "The expression level of VEGF-A in hereditary paraganglioma associated with inactivation of the SDHD gene was higher than those observed in sporadic tumors." (PMID 24675699, 2014).
paraganglioma (continued). "A consistent loss or decrease in expression of SDHD, a recessive gene involved in paragangliomas, was noted in both tumor sets." (PMID 25023465, 2014). "Previous studies demonstrated that SDHB-, SDHC-, and SDHD-related paragangliomas and GIST all show loss of SDHB immunohistochemical expression." (PMID 22974104, 2012). "Heterozygous germline mutations in SDHA, SDHB, SDHC, and SDHD cause hereditary paragangliomas and pheochromocytomas, and germline mutations in SDHB and SDHC were found to be associated with gastrointestinal stromal tumors." (PMID 22995659, 2012). "In the second dataset, comprising 30 pheochromocytomas and paragangliomas, we detect a novel founder mutation of the SDHD gene, present in only two samples." (PMID 22567117, 2012). "The persistent expression of SDHA protein in SDHA non-mutated GIST is in accordance with previous studies which showed consistent SDHA protein expression in SDHB-, and SDHD-mutated paraganglioma." (PMID 22974104, 2012). "Although nearly all familial paraganglioma in the Netherlands is accounted for by the Dutch SDHD founder mutations p.Asp92Tyr and p.Leu139Pro, several Dutch families carrying an SDHB mutation were recently identified." (PMID 19368708, 2009). "A striking aspect of the natural history of SDHD-linked paraganglioma is the parent-of-origin inheritance of tumor susceptibility." (PMID 19956719, 2009). "In our population, the majority of hereditary paraganglioma cases are associated with two founder mutations in the SDHD gene on 11q23." (PMID 19432956, 2009). "The striking parent-of-origin inheritance pattern of SDHD-linked tumors in man strongly suggests the involvement of an imprinted locus in paragangliomas." (PMID 19956719, 2009). "Germline mutations of the tumor suppressor genes SDHB, SDHC and SDHD play a major role in hereditary paraganglioma and pheochromocytoma." (PMID 19368708, 2009). "The substituted amino-acid is located within a region of the SDHD protein frequently altered due to germline mutations in paraganglioma (PGL) families (loss of Y93 and two missense mutations, i.e. D92Y and L95P)." (PMID 15331017, 2004). "The deleted region harbours the tumour suppressor gene SDHD that is frequently mutated in paraganglioma and pheochromocytoma, which are, like neuroblastoma, tumours originating from the neural crest." (PMID 15331017, 2004). "In a recent study, it was once reported that a somatic mutation in the SDHD gene, namely a c.365A > G (p.Lys122Arg) substitution located in exon 4, could be associated with dog paraganglioma." (PMID 39649680, 2024). "There was a statistically significant difference between Pheo, HNPGL and paragangliomas in other locations according to SDHD mutation presence (P<0.029), malignancy potential according to PASS (over 3 or equal and lower 3) (P<0.0002) and, Ki-67 index (over 3 or equal and lower 3) (P<0.0007)." (PMID 34181326, 2021). "None of the three SDHD variants associated with mitochondrial complex II deficiency have been previously linked to tumourigenesis, including in this extended Palestinian family, although a Dutch founder familial paraganglioma SDHD variant c.274G > T; p.(Asp92Tyr) has been described." (PMID 34012134, 2021). "Thus, we assume that the variant found in the SDHD gene is a driver mutation and its co-occurrence with other mutations in each of the three tumors can lead to the development of paraganglioma via different molecular pathways." (PMID 32948182, 2020). "SDHD variants were observed in the majority of the patients with bilateral/multiple paragangliomas." (PMID 33391357, 2020). "Moreover, most multiple paragangliomas are associated with SDHx variants, predominantly SDHD mutations, which are in accordance with our results." (PMID 32948182, 2020). "Screening for SDHB and SDHD mutations may be also be prudent in patients with paragangliomas in certain uncommon locations such as the mediastinum or the organ of Zuckerkandl." (PMID 30456751, 2018).
paraganglioma (continued). "SDHAF2 mutations may present similarly to mutations in SDHA, SDHB, SDHC and SDHD as paraganglioma and pheochromocytoma." (PMID 26839416, 2016). "Interestingly, all the tumors with a SDHB or SDHD mutation in our series corresponded to paragangliomas and, in this subgroup of patients, combined measurement of CgA, WE-14 and EM66 also provided 100% sensitivity." (PMID 24523932, 2014). "The SDHD mutations or chronic hypoxic exposure cause paragangliomas in the carotid body (CB)." (PMID 17487275, 2007). "Furthermore, SDHB or SDHD mutations were detected in the majority of patients with organ of Zuckerkandl paragangliomas, another rare site of paraganglioma occurrence located around the origin of the inferior mesenteric artery and extending to the level of the aortic bifurcation." (PMID 30456751, 2018). "The lack of differential gene-expression of chromosome 11 genes between the paraganglioma subgroups might further indicate that chromosome 11 loss, as demonstrated in SDHD-linked paragangliomas, is an important feature in the formation of a paraganglioma regardless of the genetic background." (PMID 19432956, 2009). "Approximately 25% to 35% of paragangliomas are often associated with hereditary conditions such as MEN type 2, von Hippel-Lindau syndrome, or mutations in the SDHB, SDHD, or RET gene." (PMID 39867070, 2024). "The association of pheochromocytoma–paraganglioma and GISTs, the so-called Carney–Stratakis syndrome, occurs more frequently in carriers of SDHA and SDHD variants." (PMID 37046734, 2023). "Wild type GIST driven by germline mutations in SDHB, SDHC, or SDHD subunits is a component of the Carney-Stratakis syndrome, an inherited predisposition syndrome characterized by the presence of GIST and paraganglioma." (PMID 36980917, 2023). "We describe the long-term culture of chiefly head and neck paragangliomas using primary tumour tissue from anonymous donors who carried succinate dehydrogenase subunit B (SDHB), subunit C (SDHC), subunit D (SDHD) or undefined gene variants." (PMID 36178902, 2022). "Mutation of SDH subunits (SDHD and SDHB) in hereditary tumors such as paraganglioma or reduction of SDHB expression in cancer results in matrix succinate accumulation which is transported to cytoplasma and secreted into the extracellular milieu." (PMID 36344992, 2022). "RET and VHL are HSP90 clients, and it has been reported that the expression of HIF-1α and HIF-2α (an HSP90 client) were implicated in the pathogenesis of paraganglioma with SDHB and SDHD mutations." (PMID 35932386, 2022). "Germline mutations in SDHA, SDHB, SDHC, and SDHD (collectively, SDHx) are associated with the development of PRL- and GH-secreting adenomas, pheochromocytomas, and/or paragangliomas, a syndrome named 3P association." (PMID 35743266, 2022). "The most frequently cited paper was published in Science in 2000, which indicated that SDHD played an important role in the pathogenesis of hereditary paraganglioma." (PMID 36185194, 2022). "Germline mutations in SDHx are a major cause of phaeochromocytoma and paragangliomas but inheritance patterns and risks differ between genes, and the penetrance of germline SDHA mutations is much lower than for SDHB, SDHC or SDHD." (PMID 35441217, 2022). "CSS by definition is due to SDHB, SDHC, and SDHD mutations and is characterized by the combination of GIST and paraganglioma inherited in an apparently autosomal dominant manner and with incomplete penetrance." (PMID 35059314, 2021). "Approximately 20% of patients diagnosed with a phaeochromocytoma or paraganglioma carry a germline mutation in one of the succinate dehydrogenase (SDHx) genes (SDHA, SDHB, SDHC and SDHD), which encode the four subunits of the SDH enzyme." (PMID 34021277, 2021). "In HNPGLs, Chromogranin A correctly predicts the result of paraganglioma surveillance more often in patients with SDHB compared with those with SDHD (77% vs. 22%, p = 0.003) and has less added benefit to standard surveillance." (PMID 35054195, 2021).